RNU6-1213P (RNA, U6 small nuclear 1213, pseudogene)
Gene: Small nuclear RNA gene on chromosome 8 (80,405,516 to 80,405,609, forward strand). Ensembl gene ENSG00000252884.
Homologues: Orthologues: chimpanzee U6 (99% identical). Paralogues in human: RNU6-1273P (88% identical), RNU6-166P (88% identical), RNU6-589P (88% identical), RNU6-19P (87% identical), RNU6-41P (87% identical), RNU6-748P (87% identical), RNU6-830P (87% identical), RNU6-1060P (86% identical), RNU6-1091P (86% identical), RNU6-1145P (86% identical), RNU6-1152P (86% identical), RNU6-15P (86% identical), and 1284 more.